VDAC1 (voltage dependent anion channel 1)
Diseases named in the same sentence as VDAC1 in open-access papers (continued):
Sharing a sentence is not in itself a finding about the gene and the disease.
lung carcinoma (continued). "In addition, high expression levels of VDAC1 gene can be detected in advanced lung cancer and tissues with larger lung cancer." (PMID 36750173, 2023). "We observed that both VDAC1 (Pearson’s r = 0.556, p<0.041) as well as iNOS (Pearson’s r = 0.64, p<0.016) correlated with EPOR expression and concluded that EPOR-expressing lung cancer cells showed an increased expression of iNOS and the mitochondrial marker, VDAC1." (PMID 36052260, 2022). "Furthermore, EPOR and VDAC1, as a surrogate of mitochondrial content correlated positively in most lung cancer types, except for large cell carcinoma." (PMID 36052260, 2022). "Indeed, VDAC1 was overexpressed in cervical cancer, nonsmall cell lung cancer, and other malignant tumors, suggesting that VDAC1 plays a vital role in high-energy demand tumor cells." (PMID 35958281, 2022). "In addition, knockdown of VDAC1 in multiple types of cancer cell lines, including colon and lung cancer cells, has been demonstrated to block proliferation and migration of the cancer cells in vitro." (PMID 33680287, 2021). "Given the role of tubulin in the regulation of VDAC1 and the discovery of VDAC1-ΔC in lung cancer, VDAC1 truncation may also play a role in metabolic alterations of CRC." (PMID 34381722, 2021). "In a recent report, it has been shown in various metastatic cell lines that by silencing the expression of the mitochondrial protein VDAC1, human glioblastoma (U-87MG), lung cancer (A549), and triple negative breast cancer (MDA-MB-231) cell lines have had an inhibited proliferation." (PMID 31139559, 2019). "In lung cancer, integrin β4/PXN/FAK complex mediates cisplatin resistance through regulating ubiquitin specific peptidase 1 (USP1) and voltage-dependent anion channel 1 (VDAC1), which are associated with mitochondrial function and maintaining genomic stability." (PMID 37770930, 2023). "Although VDAC1 is also differentially expressed by apoptotic regulation, we propose that the approximately 27% (r2 squared Pearson) of VDAC1 variation among the lung cancer biopsies, which was explained by EPOR expression, reflects differences in mitochondrial content." (PMID 36052260, 2022). "Finally, EPOR expression and the expression of the mitochondrial marker VDAC1 are positively correlated in biopsies of human non-small lung cancer patients, suggesting that the herein-reported mechanisms exist in tumors of human (lung) cancer patients." (PMID 36052260, 2022). "The voltage-dependent anion channel 1 (VDAC1) is the mitochondrial protein that controls cell energy, metabolic homeostasis, and apoptosis and is highly expressed in different tumors, including lung cancer, pointing to its significance in high energy-demanding cancer cells." (PMID 34200480, 2021). "In summary, in tumours derived from GBM, breast and lung cancers, regardless of the cellular origin or mutations carried, VDAC1 depletion led to similar metabolic reprogramming, including reversal of the cancer cell’s metabolic adaptation as controlled by the AMPK and mTOR signalling pathways." (PMID 30544833, 2018). "We have previously shown that VDAC1-ΔC formation is mitochondrial and is dependent on nuclear HIF-1α in a lung cancer model." (PMID 32194829, 2020). "Here, we compared the effects of downregulated VDAC1 expression in the U-87MG glioblastoma, MDA-MB-231 triple-negative breast cancer (TNBC), and A549 lung cancer cell lines, using small interfering RNA (siRNA) specific to human VDAC1 (si-hVDAC1)." (PMID 31195298, 2019). "VDAC1-based peptides (N-Ter and LP4 derived sequences) were shown to limit Ca2+ uptake into the mitochondrial matrix and inhibit ROS generation in lung cancer cells." (PMID 28824871, 2017). "A truncated form of the voltage-dependent anion channel 1 (VDAC1) is induced by HIF-1α to promote cancer cell survival and correlates with chemotherapy resistance in lung cancer patients." (PMID 23241400, 2012).
lung carcinoma (continued). "To validate whether EPOR contributes to the regulation of mitochondrial biogenesis in human lung cancer patients, we analyzed EPOR, iNOS, and VDAC1 expression in lung adenocarcinoma tissue from 19 human patients using immunohistochemistry." (PMID 36052260, 2022). "In our previous studies, we demonstrated, both in vitro and in mouse xenograft models of human glioblastoma (U-87MG), lung cancer (A549), and triple negative breast cancer (MDA-MB-231), that silencing VDAC1 expression using human-specific siRNA (si-hVDAC1-2A) inhibited cancer cell growth." (PMID 34200480, 2021). "Our strategy involved specifically silencing the expression of VDAC1 in the mitochondria of human-derived A549 lung cancer xenografts in mice, but not in the mouse-derived cells of the TME." (PMID 34200480, 2021). "The finding that si-hVDAC1-2A specifically targets human VDAC1 mRNA allows its effect to be on human A549 lung cancer cell-derived xenografts, but this does not affect the mouse host cells within the tumor." (PMID 34200480, 2021). "Here, we demonstrated that, in a urethane-induced lung cancer mouse model, the Retro-Tf-D-LP4 peptide reached the lung and attenuated tumor growth, and also decreased the expression of metabolic-related enzymes such as VDAC1 and the TCA cycle enzyme citrate synthase." (PMID 39272828, 2024). "However, VDAC1 is overexpressed (upregulated) in cervical carcinoma (Hela cell line), adrenocortical carcinoma (Human SW13 and H295R), myeloma, lung cancer, non-small cell lung carcinoma, human gastric carcinoma, and ovarian and endometrial carcinoma (OV-TRL12B, EN-TRL 67 T cell line)." (PMID 37046443, 2023). "Similarly, we showed that, upon VDAC1 depletion in the A549 lung cancer cell line, representing non-mature AT2 cells, the expression of SFTP C was increased after the third and fourth transfections." (PMID 31195298, 2019). "Analysis of lung tissue microarrays for VDAC1 and AIF (10 healthy, 31 SCC and 21 AC) and for SMAC (20 healthy, 72 SCC and 72 AC) expression levels by IHC staining using specific antibodies revealed high expression of these proteins in lung cancer, as compared to healthy tissue." (PMID 29285267, 2017). "Similarly, we showed that upon VDAC1 depletion in tumours derived from the A549 lung cancer cell line, representing non-mature AT2 cells, the residual tumour showed increased expression of the pulmonary-associated surfactant protein C, SP-C, although SP-A1 and SP-B levels were decreased." (PMID 30544833, 2018).
Alzheimer disease (38 papers, 2013 to 2025). A progressive, neurodegenerative disease characterized by loss of function and death of nerve cells in several areas of the brain leading to loss of cognitive function such as memory and language. "In Alzheimer's disease (AD), VDAC1 is overexpressed in affected brain regions and is associated with neuronal cell death and mitochondrial dysfunction, key features of AD pathology." (PMID 40285415, 2025). "In this content, VDAC1 overexpression has been implicated in many diseases including cancer, Alzheimer’s disease (AD), Parkinson’s disease (PD), amyotrophic lateral sclerosis (ALS), type 2 diabetes (T2D), cardiovascular diseases, and autoimmune diseases." (PMID 40362204, 2025). "Increased levels of Vdac1 have been shown to be associated with the progression of diseases involving cognitive impairment, such as Alzheimer’s disease and neonatal hypoxia–ischemia." (PMID 38455734, 2024). "Accordingly, increasing evidence suggests that VDAC1 is implicated in the pathophysiology of neurodegenerative diseases, including Alzheimer’s disease (AD), Parkinson’s disease (PD), amyotrophic lateral sclerosis (ALS), and others." (PMID 39858428, 2024). "These, together with its overexpression in cancer and other diseases, including Alzheimer’s disease, some cardiovascular diseases and type 2 diabetes, suggest that VDAC1 overexpression is associated with cell response to stress conditions." (PMID 33114780, 2020). "VDAC1 upregulation and oligomerization is caused by oxidative and nitrosative stress, not only in β-cells in T2D but also in neurodegenerative diseases, in particular, Alzheimer’s disease." (PMID 36979492, 2023). "VDAC1 has been implicated in neuronal cell death in both Alzheimer's disease (AD) and PD." (PMID 27859782, 2017). "In addition, reduced expression of miR-29 family causes several neurodegenerative disorders, including Alzheimer’s disease, Huntington’s disease, and spinocerebellar ataxias, by targeting voltage-dependent anion channel 1 (VDAC1), β-secretase 1 (BACE1) and neuron navigator 3 (NAV3)." (PMID 29495532, 2018). "VDAC1 has been implicated in the control of apoptosis, including via its interaction with the pro- and anti-apoptotic proteins and due to an abnormal interaction with amyloid beta and phosphorylated tau, is implicated in mitochondrial dysfunction in Alzheimer’s disease." (PMID 23506439, 2013). "The use of a small, synthetic VDAC1‐antagonist peptide, derived from hexokinase, restores mitochondrial functionality, and respiration in cellular models of Alzheimer's disease." (PMID 40223243, 2025). "VDAC1 plays a critical role in promoting ferroptosis during tissue damage and organ dysfunction in various diseases including cancer, Alzheimer’s disease, liver injury, and myocardial infarction." (PMID 39521767, 2024). "Vdac1 undergoes PTMs due to oxidative stress, which is another critical pathological factor in Alzheimer’s disease development." (PMID 38455734, 2024). "Previous studies also unveiled that a portion of VDAC1 appears on other membrane systems, including the ER and plasm membrane, especially in conditions like type 2 diabetes, Alzheimer’s disease, and virus infection." (PMID 38517390, 2024). "VDAC1 inhibition alleviates ferroptosis by protecting mitochondria in acetaminophen-induced acute liver injury and Aβ1-42-induced Alzheimer’s disease in mice." (PMID 39521767, 2024). "It is, therefore, of great interest that VBIT-4, which inhibits VDAC1 conductance and oligomerization, prevents onset of diabetes in db/db mice and markedly improves the phenotype in a mouse model of Alzheimer’s disease." (PMID 36979492, 2023). "We recently found that VDAC1 is over-expressed not only in cancer, but also in several diseases such as Alzheimer’s disease (AD), type 2 diabetes (T2D), and autoimmune diseases such as lupus and colitis." (PMID 36077343, 2022).
Alzheimer disease (continued). "In post-mortem brain of patients with Down Syndrome (DS) and Alzheimer’s disease (AD), the levels of VDAC1 and VDAC2 were altered." (PMID 34671273, 2021). "In particular, the principal isoform VDAC1 represents the main mitochondrial docking site of many misfolded proteins, such as amyloid-β and Tau in Alzheimer’s disease, α-synuclein in Parkinson’s disease, and several SOD1 mutants in ALS." (PMID 34884639, 2021). "The levels of pl-VDAC1 were reported to be increased under pathological conditions such as Alzheimer’s disease (AD), where it has been suggested that pl-VDAC1 serves as an “amyloid-regulated” apoptosis related channel." (PMID 33114780, 2020). "Alzheimer's disease is characterized by an enanched expression levels of VDAC1 and by reduced interaction of VDAC1 with the glycolityc enzymes HKs." (PMID 29682501, 2018). "There are increasing data pointing to the medical relevance of cell membrane-standing VDAC-1 by its involvement in the pathogenesis of several syndromes, e.g., cancer, cystic fibrosis, Alzheimer's Disease, autism, and malaria." (PMID 25964761, 2015). "In post mortem brains of Alzheimer’s disease patients, VDAC-1 is overexpressed, and therefore, prodromal Alzheimer’s disease might be recognized by VDAC-1 overexpression as a biomarker." (PMID 38474278, 2024). "Indeed, some results suggest that VDAC1 phosphorylation is involved in the genesis of apoptosis in brain of Alzheimer disease (AD) and Down syndrome (DS) patients." (PMID 34884639, 2021). "Decreased Vdac1 expression was beneficial to synaptic activity and improved function, and could alleviate Alzheimer's disease." (PMID 33078551, 2020). "This, together with its over-expression in cancer and other diseases, including Alzheimer’s disease, some cardiovascular diseases and type 2 diabetes, involves VDAC1 in the cell stress response and thus represents a target to modulate the biology of cancer and other diseases." (PMID 30542671, 2017). "VDAC1 overexpression, its oligomerization, and apoptosis were triggered by various apoptosis-inducing conditions including chemotherapy drugs and UV irradiation in several disorders such as Alzheimer’s disease, type 2 diabetes, and autoimmune diseases such as lupus and inflammatory bowel diseases." (PMID 39375263, 2024). "Our current study aimed to understand the impact of a partial reduction of voltage‐dependent anion channel 1 (VDAC1) protein on mitophagy/autophagy, mitochondrial and synaptic activities, and behavior changes in transgenic TAU mice in Alzheimer's disease." (PMID 35801276, 2022). "Accumulated data showed that VDAC1 overexpression is common in many diseases (T2DM, cancer, Alzheimer’s’ disease, Parkinson’s disease, cardiovascular diseases, and more) that are affected by metformin-affecting diseases." (PMID 34671273, 2021). "In a special form of lipid rafts called caveolae, pl-VDAC-1 was accumulated, and its interaction with mERα was altered in the human cortex and hippocampus derived from patients suffering from Alzheimer’s disease (AD) compared to non-pathological samples." (PMID 38474278, 2024).
glioblastoma (25 papers, 2017 to 2025). The most malignant astrocytic tumor (WHO grade IV). "The deletion of VDAC1 has been shown to cause glioblastoma (GBM) metabolism rewiring, which can, in turn, affect epigenetic modification and inhibit tumor development and progression." (PMID 35185897, 2022). "Similar findings were observed in glioblastoma CSCs, where VDAC1 silencing led to a decrease in mitochondrial ATP production and increased sensitivity to chemotherapy." (PMID 40608151, 2025). "We showed that, as in our previous results obtained with lung, glioblastoma, breast, and other cancer types, VDAC1 depletion resulted in multifactorial responses in cell metabolism, proliferation, angiogenesis, stemness, and differentiation." (PMID 38607066, 2024). "VDAC1 is highly expressed in glioblastomas, exhibiting its significance in high energy-demanding cancer cells." (PMID 36768856, 2023). "Studies have shown that the reduction of VDAC1 in patient-derived glioblastoma cell lines by way of si-RNA reduced cellular ATP levels and inhibited tumor development and growth." (PMID 36768856, 2023). "To this end, we used DNA microarrays, q-PCR, and specific antibodies to analyze the effects of si-VDAC1 treatment of glioblastoma tumors on the expression of epigenetic-related genes." (PMID 32331482, 2020). "Following depletion of VDAC1 in cancer cells in a glioblastoma tumor, we detected epigenetic alterations in the level of histone modifications at the methylation and acetylation states and in epigenetic-related enzyme expression levels." (PMID 32331482, 2020). "The OMM-localized 18 kDa translocator protein (TSPO) is demonstrated to inhibit mitochondrial Ca2+ uptake by promoting VDAC1 phosphorylation, while VDAC1 ablation in human glioblastoma U87 cells leads to reduced levels of TSPO." (PMID 33195204, 2020). "We recently demonstrated that depleting VDAC1 in glioblastoma cells U87-MG-derived tumors affects the metabolism–epigenetics axis of the tumor." (PMID 33114780, 2020). "Inhibition of VDAC1 expression by siRNA suppresses cell proliferation and tumor growth in cancers, including lung, prostate, colon, glioblastoma, liver and pancreas cancer." (PMID 32210729, 2020). "Our findings that down-regulation of VDAC1 in glioblastoma also down-regulated TSPO expression suggests that this should affect the tumor functions supported by TSPO such as metabolism, and cell proliferation." (PMID 31661894, 2019). "After silencing VDAC1 expression in cancer cells for an extended period of 10–15 days, significant reductions in glioblastoma cancer stem cell (GSC) markers were observed, accompanied by morphological changes indicative of differentiation into more mature, normal-like cells." (PMID 39456237, 2024). "In our recent study, we demonstrated that down-regulation of VDAC1 in glioblastoma (GBM) also down-regulated TSPO expression." (PMID 31288390, 2019). "The most active Vern plant extract induced VDAC1 overexpression in both cell lines tested: the neuroblastoma-derived cell line SH-SY5Y and glioblastoma-derived U-87MG cell line." (PMID 36900417, 2023).